CALU (calumenin)
Diseases named in the same sentence as CALU in open-access papers (continued):
Sharing a sentence is not in itself a finding about the gene and the disease.
Ssc (1 paper, 2021). "The regulatory function of calumenin in tissues that are affected by the processes of cytoskeleton rearrangement points out calumenin as a candidate prognostic biomarker in Ssc patients, like has been previously suggested for another member of the CREC family (reticulocalbin 1)." (PMID 34063287, 2021). "Having such an influence upon wound healing via fibroblast activity modulation calumenin could be an interesting and promising biomarker for Ssc patients as it has been previously isolated from biological samples from Ssc patients using mass spectrometry." (PMID 34063287, 2021). "In conclusion, this study confirmed circulatory cytohesin 2, calumenin and S100A6 as biomarkers in Ssc patients and found associations between the serum levels of these biomarkers and clinical characteristics, especially with severe cutaneous involvement (necrosis and diffuse sclerosis)." (PMID 34063287, 2021). "The results of the current study confirmed circulatory calumenin, S100A6 and cytohesin 2 as biomarkers for SSc patients." (PMID 34063287, 2021).
Stroke (1 paper, 2011). Sudden impairment of blood flow to a part of the brain due to occlusion or rupture of an artery to the brain. "The second paper evaluated the roles of VKORC1, gamma-glutamyl carboxylase (GGCX), calumenin (CALU), and cytochrome P450 2C9 (CYP2C9) in warfarin maintenance dose on Japanese stroke sufferers." (PMID 22135769, 2011).
cancer (23 papers, 2016 to 2025). A tumor composed of atypical neoplastic, often pleomorphic cells that invade other tissues. "As a hallmark gene of the EMT process, calumenin (CALU) was previously reported to directly impact cancer metastasis." (PMID 34150647, 2021). "Enrichment analysis revealed that these genes were associated with various diseases and functions, including cancer, organismal injury and abnormalities, cellular development, cellular growth and proliferation, cellular movement, cell death and survival following CALU knockdown." (PMID 38970088, 2024). "Interestingly, cancer cells were shown to increase the CALU secretion from the cancer-associated fibroblasts (CAFs) via a TGF-β induced miR-21 expression axis and promoted tumoral proliferation and metastasis." (PMID 32469983, 2020). "After treatment with FUS‐induced hyperthermia effect, several markers associated with cancer progression and drug resistance were down‐regulated, such as major vault protein (MVP), calumenin (CALU), and heat shock 70 kDa protein 5 (HSPA5)." (PMID 38041509, 2024). "The expression pattern of CALU varies across different cancer types, suggesting its multifaceted and context-specific mechanism of action." (PMID 38970088, 2024). "Increasing evidence indicate that overexpression of CALU promotes cancer cell growth, migration, invasion and metastasis." (PMID 37723418, 2023). "Strikingly, a number of proteins that are known to play important roles in cancer progression and invasion, such as Podocalyxin and inhibitory Calumenin, were found upon PTEN inhibition with increased or decreased basolateral levels, respectively." (PMID 36555834, 2022). "Calumenin (CALU), a hallmark gene of the EMT process, was previously reported to directly impact cancer metastasis in multiple cancers." (PMID 34150647, 2021). "A pan-cancer analysis on the association of CALU with HSPA5, GPX4 and SLC7A11 further confirmed the potential involvement of CALU in the regulation of ferroptosis." (PMID 34150647, 2021). "The current study was aimed to identify CALU co-expressed genes, their signaling pathways, and expression status within the human cancers." (PMID 32469983, 2020). "Reticulocalbin and calumenin are both highly increased at the protein level in the cancer cell line (p < 0.001, p < 0.01)." (PMID 32422974, 2020). "This investigation was in line with the previous study of identifying the potential biomarkers of colorectal carcinogenesis, in which reported the CALU as one the metastasis-related proteins upregulated from adenoma to carcinoma." (PMID 32469983, 2020). "Further study is needed to clarify the functional mechanism of CAF-derived calumenin on cancer cell proliferation." (PMID 29892003, 2018). "MiR-21-expressing CAFs then promote the proliferation of cancer cells through the secretion of calumenin." (PMID 29892003, 2018). "Calumenin (CALU) is a calcium-binding protein involved in several physiological processes, exhibiting tumor-specific expression variation and emerging as a potential player in cancer progression." (PMID 40922754, 2025). "Understanding these mechanisms and their association with different CALU isoforms could lead to the development of CALU-targeted therapeutic interventions tailored to specific types of cancer, thus offering a promising path for clinical translation." (PMID 40922754, 2025). "However, there is limited research on CALU in malignant tumors, and the understanding of its mechanisms in cancer is still nascent." (PMID 38970088, 2024).
cancer (continued). "High expression of CALU promotes the progression of LUAD by inhibiting a variety of cancer-inhibiting pathways and activating classical cancer-promoting pathways, therefore, CALU may be an important therapeutic target for LUAD." (PMID 38970088, 2024). "Understanding these mechanisms could facilitate the development of small molecule compounds targeting CALU for therapeutic interventions tailored to different cancer types, thereby offering a promising avenue for clinical translation." (PMID 38970088, 2024). "In addition, calumenin (CALU) is regarded as a symbolic gene of the EMT process that impacts cancer metastasis in various types of tumors." (PMID 37886960, 2023). "However, considering the lack of knowledge about the calumenin association with other signaling mediators, we tried to visualize and analyze calumenin co-expressed genes network in human cancers." (PMID 32469983, 2020). "Moreover, the protein band recognized by the calumenin antibody decreases slightly in size in the cancer cell line as compared with the normal derived cell line." (PMID 32422974, 2020). "Calumenin (CALU) is one of these factors which has a direct impact on cancer metastasis and yet, its underlined mechanisms have not been completely elucidated." (PMID 32469983, 2020). "Calumenin was expressed in cancer cells and in miR-21-expressing stromal cells." (PMID 29892003, 2018). "Depending on the splice isoform, calumenin (CALU) expression has been shown to both promote and inhibit cell migration, so that its role in tumour metastasis may differ between cancer types." (PMID 27876705, 2016). "However, in tumor microenvironment, CALU was reported to play a critical role in promoting a series of malignant phenotypes including cancer cell survival, filopodia formation and cell migration, invasiveness, metastasis, cancer development, and resistance to chemotherapy." (PMID 33623713, 2021). "However, suggested as an EMT-related gene, CALU could also be highly expressed in tumor cells, which indicated the crucial roles of CALU in cancer progression other than the function of inducing EMT." (PMID 34150647, 2021). "In summary, our findings indicate that CALU is significantly upregulated in LUAD and contributes to the progression of this cancer by promoting the migration and proliferation." (PMID 38970088, 2024). "CALU (Calumenin), as a pivotal gene of the EMT process, has been reported to directly link to the cancer metastasis of a variety of cancers." (PMID 35789544, 2023). "Diagnostic accuracy estimation of differentially expressed genes showed that a gene panel consisted of CALU, AURKA, and MCM2 was able to successfully distinguish cancer tumors from healthy samples." (PMID 32469983, 2020). "Western blot analysis of CALU, AURKA, and MCM2 proteins showed that the level of all of these candidate biomarkers was statistically increased through normal–carcinoma transition in both types of cancers." (PMID 32469983, 2020). "The CPTAC data similarly revealed a correlation between high CALU protein expression and advanced stages or advanced grades in LUAD, indicating that higher protein expression levels corresponded to increased cancer progression." (PMID 38970088, 2024). "Cancer cell-derived TGF-β1 activates miR-21 expression in LNFs and induces differentiation to CAFs, which promote the proliferation of cancer cells through the secretion of calumenin." (PMID 36672284, 2023). "Diagnostic accuracy analysis of these DEGs in TCGA datasets COAD and LUAD showed that a gene panel that consists of CALU, AURKA, and MCM2 could successfully distinguish cancer tumors from healthy samples." (PMID 32469983, 2020).
cancer (continued). "In summary, analysis of CALU co-expressed genes network as one the key regulators in tumor metastasis introduced a gene panel that consists of CALU, AURKA, and MCM2 with high discriminative accuracy between healthy and cancer (colon and lung) populations." (PMID 32469983, 2020). "Additionally, comparison of CALU, AURKA, and MCM2 proteins between healthy samples, early and advanced tumors showed that the level of these proteins was increased through normal–carcinoma transition in both types of cancers." (PMID 32469983, 2020). "Interestingly, CALU, directly interacting with DDOST and RPN2, is known to be highly expressed in tumor cells and therefore might play a crucial role in cancer progression and the induction of epithelial-to-mesenchymal transition." (PMID 39223141, 2024). "Distinct from the extracellular effect of CALU-1/− 2 in downregulated cancers, CALU-15 facilitated the nuclear expression of nucleus GDF-15, which then mainly promoted cell migration and tumour metastasis; our study confirmed that CALU promoted the expression of GDF-15." (PMID 31118065, 2019).
tumor (23 papers, 2015 to 2025). "Calumenin as a molecular chaperone that not only binds various proteins within the endoplasmic reticulum but also plays crucial roles in diverse processes associated with tumor development." (PMID 38970088, 2024). "CALU may be involved in tumor microenvironment remodeling because of its close association with CD8 cells and macrophages." (PMID 35789544, 2023). "CALU plays a critical role in tumor cell survival, invasion, and metastasis by binding to endoplasmic reticulum proteins and regulating endoplasmic reticulum homeostasis." (PMID 41595468, 2025). "Our analysis also showed that anti-tumor effect of CALU is related to the activation of the ubiquitin system and inhibition of the Nucleotide-Binding Oligomerization Domain 1/2 (NOD1/2) and PKA pathways." (PMID 38970088, 2024). "The differential expression of CALU was analyzed in 515 tumor tissues and 59 normal tissues using The Cancer Genome Atlas (TCGA), revealing significant differences between lung tumor tissues and their corresponding normal counterparts." (PMID 38970088, 2024). "Calumenin inhibits cell migration and tumor metastasis through FN, SDC4 and α5β1-integrin by the suppression of ERK1/2 signaling." (PMID 34282767, 2021). "Studies have correlated calumenin (CALU) with tumor cell proliferation ability, with CALU transcript levels observed to be highly upregulated in GBMs 30,31." (PMID 32642004, 2020). "Consistent with conferral of a tumor-suppressive phenotype, we observed that CALU was significantly downregulated in GEVs treated with FUS (p<0.0001)." (PMID 32642004, 2020). "Both reticulocalbin and calumenin were found with high expression in the tumor compared to the healthy part of colon and must therefore be seen as potential markers of CRC." (PMID 32422974, 2020). "Based on this finding, we speculate that the role of CALU in PAAD may differ from that in other tumor types, or that its function in PAAD progression is complex and cannot be fully defined at the transcriptional level." (PMID 41595468, 2025). "TFRC and CALU may help tumor cells cope with metabolic stress, such as ferroptosis and endoplasmic reticulum stress." (PMID 41595468, 2025). "Additionally, protein expression analysis was conducted using the Clinical Proteome Tumor Analysis Consortium (CPTAC) database confirmed the elevated expression of CALU in primary LUAD tumor samples." (PMID 38970088, 2024). "This suggests that CALU may be secreted into the tumor microenvironment through exocrine pathways, inhibition of CALU enhances anti-tumor immunity and inhibiting tumor progression." (PMID 38970088, 2024). "CALU may play a unique role in the EMT process of MSI tumor patients by affecting the function of ERK." (PMID 35789544, 2023). "Interestingly, we observed adjacent glandular cystitis (GC), a precancerous lesion of BLCA, and tumor tissue in the same section, and the expression of CALU in tumor cells was significantly higher than that in GC." (PMID 34150647, 2021). "Based on the results of gene enrichment analysis, we have identified that CALU may regulate various tumor microenvironment components." (PMID 34150647, 2021). "According to the vital role of calumenin in tumor metastasis, it could be considered as a potential target for anticancer therapy." (PMID 32469983, 2020). "All 30 DEPs were significantly correlated with DDOST in 179 PAAD tumor tissue samples, among which 22 were strong correlations, including RPN2, SERBP1, CALU, STT3B, YWHAZ and MAPK1." (PMID 39223141, 2024). "RCN3 (r = − 0.319, p < 0.05) and CALU (r = – 0.215, p < 0.05) expressions had significantly negative correlations with tumor purity, while a weak negative correlation was observed between SDF4 expression and tumor purity (r = − 0.125, p < 0.05)." (PMID 37723418, 2023).
tumor (continued). "We found two of the three CREC proteins analyzed, reticulocalbin and calumenin, to be increased in the tumor cell line SW480, and both of them were also expressed to a higher degree in tumor biopsies (peripheral and central part) both compared to the non-involved part of the colon." (PMID 32422974, 2020). "Notably, CALU, TFRC, and GBP2 were highly expressed in early developmental stages, whereas SERPINB5 and LY6D were up-regulated in later phases, indicating their involvement in distinct stages of cellular state transitions and tumor progression." (PMID 41595468, 2025). "We then analyzed CALU, KIF1B, and POLR3G expression in TCGA database and NPC microarray GSE53819, the results showed that CALU and POLR3G are highly expressed in HNSC tumor tissues while KIF1B is not significant, but all of them are highly expressed in NPC tissues in GSE53819." (PMID 39964093, 2025).
adenocarcinoma (2 papers, 2020 to 2024). A common cancer characterized by the presence of malignant glandular cells. "We have compared the protein expression of three members of the CREC family reticulocalbin, calumenin and ERC-55 in a CRC cellular model, i.e., a normal derived colon mucosa (NCM460) cell line and a cell line established from a primary adenocarcinoma of the colon (SW480)." (PMID 32422974, 2020).
intestinal diseases (1 paper, 2024). "Relevant proteins such as CALU, FLNA, MSN and HMGA2, which are related to intestinal diseases, were all upregulated in the IBD duodenal organoids." (PMID 38203746, 2024).
CALU also shares sentences with these, for which no sentence is quoted: colorectal cancer (2 papers); infection (2); amyloidosis (1); autoimmune (1); cecum adenocarcinoma (1); colon (1); diabetes (1); dilated cardiomyopathy (1); head and neck squamous cell carcinoma (1); hepatocellular carcinoma (1); ischemic cardiomyopathy (1); metabolic syndrome (1); mucinous adenocarcinoma (1); mucosal (1); muscular dystrophies (1); neuroblastoma (1); Obesity (1); oligodendroglioma (1); pancreatic cancer (1); psoriasis (1); pulmonary arterial hypertension (1); rectal adenocarcinoma (1); sarcoma (1); squamous cell carcinoma (1).